LINC02147 (long independently transcribed non-coding RNA 2147)
Synonyms: LOC124901051
Gene: Long non-coding RNA gene on chromosome 5 (117,730,251 to 118,266,267, forward strand). Ensembl gene ENSG00000249797.
Diseases named in the same sentence as LINC02147 in open-access papers:
LINC02147 is named in the same sentence as 1 disease in open-access papers, as found by Europe PMC text mining. Sharing a sentence is not in itself a finding about the gene and the disease.
LINC02147 shares sentences with these, for which no sentence is quoted: oral submucous fibrosis (1 paper).